NPAS2 (neuronal PAS domain protein 2)
Diseases named in the same sentence as NPAS2 in open-access papers (continued):
Sharing a sentence is not in itself a finding about the gene and the disease.
tumor (continued). "Moreover, Bmal1 can heterodimerize with NPAS2, bind to the E-box element in the promoter region of CDC25A and participate in NPAS2-mediated tumor cell survival in HCC." (PMID 31139087, 2019). "The stable knockdown of NPAS2 in HLE cells resulted in a significantly decreased tumor growth in xenograft model mice, whereas the growth capacity of xenograft tumors developed from HLF cells with stable overexpression of NPAS2 was much higher than control xenograft tumors." (PMID 28333141, 2017). "Notably, tumor-suppressive roles have been reported for CAMK2B, EGR3, NPAS2, PCDH8, and RGS6." (PMID 39796709, 2024). "NPAS2 up-regulation in UCEC tissue samples compared to matched non-tumorous tissue was associated with more advanced clinical stage and tumor grade, estrogen receptor status, myometrial invasion, leading to decreased overall, disease-free and relapse-free survival in UCEC patients." (PMID 37887064, 2023). "In addition, the myelocytomatosis oncogene cellular homolog (Myc) proto-oncogene is thought to be regulated by BMAL1/neuronal PAS domain protein 2 (NPAS2) (a CLOCK paralogue) action on its E-boxes, which may contribute to enhanced tumor growth in Per2 mutant mice in response to DNA damage." (PMID 31039152, 2019). "This may suggest that tumor suppressing circadian genes (PER1,2,3, NPAS2) are particularly relevant for ER/PR negative tumorigenesis." (PMID 29958276, 2018).
cancer (41 papers, 2014 to 2025). A tumor composed of atypical neoplastic, often pleomorphic cells that invade other tissues. "Its regulation of HIF-1α and association with miR-199 b-5p further promote cancer growth, making NPAS2 a key player in circadian metabolism regulation and a potential therapeutic target in HCC." (PMID 39566400, 2024). "Circadian positive feedback loop (CPFL) genes (CLOCK, BAML1, and NPAS2) have been implicated in cancer initiation and progression." (PMID 30843665, 2019). "This circadian-cancer link was confirmed in a meta-analysis showing association between risk of cancer and variants in NPAS2, RORA, RORB, and CLOCK." (PMID 31303884, 2019). "The genes that contributed the most to the overall association with cancer risk were NPAS2, CLOCK and RORs (RORA and RORB)." (PMID 28177907, 2017). "Furthermore, NPAS2 is implicated in pathological mechanisms of disease, such as those pushing cancer onset and progression." (PMID 37887064, 2023). "In addition, some studies have already demonstrated different NPAS2 polymorphisms’ expression as a risk biomarker in other types of cancer." (PMID 35897788, 2022). "Future research should explore the roles of ZNF697, NPAS2, and genomic reorganization in polyploid cancer cells and their implications for disease recurrence in progeny cells." (PMID 39578659, 2025). "The univariate Cox of overall survival (OS) was performed to evaluate if the differential expression of NPAS2 was related to the prognosis of patients with different cancer types." (PMID 38291048, 2024). "Mutations and copy number variations in circadian clock genes, such as ARNTL2 in colorectal cancer and NPAS2, CLOCK, and PER3 in breast cancer, are linked to cancer progression, suggesting their potential as biomarkers for cancer risk and prognosis." (PMID 39566400, 2024). "Future research should explore the roles of ZNF697 and NPAS2 in polyploid cancer cells and their implications for disease recurrence in progeny cells." (PMID 39483900, 2024). "NPAS2 was found to be clinically relevant and involved in the regulation of subtype-specific genes influencing cancer cell proliferation and migration in luminal bladder cancer." (PMID 37887064, 2023). "For example, the BMAL1-CLOCK/NPAS2 heterodimer has been reported to repress c-Myc, an oncogene that contributes to the genesis of many human cancers, and whose protein expression is closely correlated with cell proliferation rates." (PMID 36768253, 2023). "Our study suggested that low Per1, Per2 and Npas2 expression played a distinct and crucial role in progression of cancers." (PMID 32437452, 2020). "Our results showed that low Per1, Per2, Per3 and Npas2 expression played a distinct and crucial role in progression of cancers." (PMID 32437452, 2020). "In conclusion, our meta-analysis provided evidence that low Per1, Per2and Npas2 expression played a distinct and crucial role in progression of cancers." (PMID 32437452, 2020). "Studies on the relationship between clock genes polymorphisms and cancer susceptibility have established that variants of ARNTL, CLOCK, CK1ε, CRY1-2, NPAS2, and PER1-3 are frequently associated to human reproductive tissues and pancreatic cancers." (PMID 30873119, 2019). "Moreover, tobacco smoke repressed the expression of the tumor suppressors Arntl and Npas2 in females, and their repression promoted cell proliferation in various cancers." (PMID 38245882, 2024). "The PER1, PER2, and PER3 genes regulate cell growth, proliferation, and apoptosis, CRY1 and CRY2 regulate the transcription G1/S and G2/M cell cycle checkpoints, while BMAL1 and NPAS2 inhibit the proliferation and invasion of cancer cells by suppressing the c-Myc transcription factor." (PMID 36672355, 2023).
cancer (continued). "Quantitative real-time PCR (qRT-PCR), immunohistochemical (IHC) staining, western blot, GEO (Gene Expression Omnibus) and CCLE (Cancer Cell Line Encyclopedia) databases were used to analyze the expression of NPAS2 in human PCa tissues and various PCa cell lines." (PMID 36978001, 2023). "For example, there is research showing that clock gene variations, particularly to NPAS2, CLOCK, RORA, RORB, and PER3, may contribute to small but statistically significantly elevated cancer risk." (PMID 36387255, 2022). "NPAS2 is a circadian gene that has attracted the interest of researchers due to its various effects on cells and various roles in disease development, especially cancer." (PMID 35880088, 2022). "However, well designed, larger-size and higher-quality cohort studies are needed to investigate the precise impact of Per1, Per2and Npas2 on the pathobiological behaviors and prognosis of cancers." (PMID 32437452, 2020). "Bmal1 and Npas2 could regulate cancer cell proliferation and invasion through suppressing the transcription of c-Myc." (PMID 32437452, 2020). "The intersection of differentially expressed genes (DEG) and our list of candidate genes, resulted in 12 elements including cancer associated genes (NRAS, MYC, and VEGFA), circadian drug targets (SOD2 and CES2) and core-clock and ECCN genes (AHR, CREB1, CSNK2A1, NFIL, NPAS2, NR1D1, and PER3)." (PMID 32295075, 2020). "All these reports suggest that the inhibition of NPAS2 serves as a therapeutic target for cancers." (PMID 29285299, 2017). "Moreover, in SMC-like cells (14D), we also observed the expression of pro-apoptotic genes, such as Alx4 and Npas2, which are frequently reported in cancer research, suggesting they may have an adverse impact on adipose tissue browning." (PMID 40118146, 2025). "Therefore, although heterogeneity existed, these pooled results suggested that low expressions of Per1, Per2, Per3 and Npas2 might play important roles in the development and progression of cancers." (PMID 32437452, 2020). "This discordance between NR1D1 and NR1D2 is a possible source of the small amplitudes in RRE-targets NPAS2, NFIL3, and CRY1 in the cancers." (PMID 40424435, 2025). "Heterogeneous distribution of CRGs was observed in cancers: clock control genes such as HLF and RORs were lowly expressed in most tumors, while core clock genes such as TIMELESS and NPAS2 were highly expressed." (PMID 36895015, 2023). "In our research, NDC80, NPAS2, and AHNAK2 were sifted out from the ISGs family to develop a signature that improved the prediction of OS for pan-cancer patients." (PMID 35813478, 2022). "We demonstrated that in vitro and in vivo cancer cells after PER1 knockdown, PER2, DEC1, DEC2, CRY1, CRY2 and NPAS2 were significantly down-regulated at the mRNA level, while PER3, TIM, RORα and REV-ERBα were significantly up-regulated." (PMID 27602964, 2016). "In our research, mRNA expression of NPAS2 was robustly decreased after PER1 knockdown, indicating that the compensatory effect on CLOCK/BMAL1 was weakened due to PER1 knockdown in cancer cells." (PMID 27602964, 2016). "Interestingly, down-regulation of PER1-3, CRY2, NPAS2, BMAL1, as well as CLOCK gene expression, correlates with high histological grade and poor prognosis and short survival in different cancers." (PMID 36672355, 2023). "This analysis validated the identification of genes that could be specific to cancer biology, such as IL7R, JUN, NR3C1 in Ba/Sq subtype, NPAS2, FOXQ1, GRHL3 in Luminal samples, or CDKN2C, FOXJ1, MEIS2, FGFR3 in both subtypes." (PMID 36944729, 2023). "Previous studies have also confirmed the opposite effects of NPAS2 and CRY2 on cancer prognosis." (PMID 35832846, 2022). "Additionally, the neuronal PAS domain protein 2 (NPAS2), a core circadian molecule analog of CLOCK, is upregulated in HCC and facilitates cancer cell survival." (PMID 34298842, 2021).
cancer (continued). "Quantitative real-time PCR result indicated that in vitro and in vivo cancer cells after PER1 knockdown, PER2, DEC1, DEC2, CRY1, CRY2 and NPAS2 were significantly down-regulated at the mRNA level, while PER3, TIM, RORα and REV-ERBα were significantly up-regulated." (PMID 27602964, 2016). "This study demonstrates that the down-regulation of PER1 in cancer cells can result in the robust up-regulation of PER3, TIM, RORα and REV-ERBα transcripts, while the expression of PER2, DEC1, DEC2, CRY1, CRY2 and NPAS2 is prominently down-regulated in vitro and in vivo." (PMID 27602964, 2016). "In order to achieve a systematic understanding of circadian clock in cancer, we define a core subset of clock family genes including 7 positive regulators (CLOCK, NPAS2, ARNTL, ARNTL2, RORA, RORB, and RORC) and 7 negative regulators (PER1, PER2, PER3, CRY1, CRY2, NR1D1, and NR1D2)." (PMID 31708917, 2019).
infection (3 papers, 2016 to 2025). The state of being infected such as from the introduction of a foreign agent such as serum, vaccine, antigenic substance or organism. "Moreover, on 3 d and 7 d post-infection, DEGs related to gut diseases were significantly affected, particularly Ceacam10, Tns4, Neu1, Serpina10, and Npas2." (PMID 39727670, 2025). "Moreover, we revealed a bipolar mode of fibroblast differentiation and put forward the hypothesis that infection could modulate fibroblast toward a pro-inflammatory phenotype through NPAS2 and TFEC." (PMID 36927352, 2023).
bacterial infection (1 paper, 2018). "Genetic ablation of neuronal PAS domain protein 2 (Npas2) exaggerates inflammatory responses to lipopolysaccharide and bacterial infection." (PMID 29086354, 2018).
NPAS2 also shares sentences with these, for which no sentence is quoted: metabolic syndrome (5 papers); psychiatric disorder (4); acute myeloid leukaemia (2); colon cancer (2); Obesity (2); pulmonary fibrosis (2); squamous cell carcinoma (2); acute myocardial infarction (1); atherosclerosis (1); atrial fibrillation (1); autism spectrum disorder (1); autoimmune disease (1); bone osteosarcoma (1); cholestasis (1); cutaneous melanoma (1); epilepsy (1); heart failure (1); inflammatory bowel disease (1); ischemia (1); liposarcoma (1); liver disease (1); lymphoma (1); malignant pleural mesothelioma (1); neurodevelopmental disorder (1); osteoporosis (1); pneumonia (1); polycystic ovary syndrome (1); rectal cancer (1); renal carcinoma (1); sarcoma (1).
A further 4 diseases each share a sentence with NPAS2 in 1 paper.